CRP (C-reactive protein)
Diseases named in the same sentence as CRP in open-access papers (continued):
Sharing a sentence is not in itself a finding about the gene and the disease.
pneumonia (continued). "The proportion of CRP testing in total for pneumonia, acute bronchitis, and cough increased from 55.3% in 2006 to 61.6% in 2014 (odds ratio [OR] 1.30; 95% confidence intervals [CI] = 1.20 to 1.40; P<0.001)." (PMID 32127365, 2020). "A study showed that when LDH and CRP levels were correlated with computed tomography scans, significantly higher levels reflected the severity of pneumonia." (PMID 33148349, 2020). "In patients with respiratory tract infection, there is an already known better CRP performance in patients with pneumonia." (PMID 32487263, 2020). "Early COVID‐19 patients with chronic comorbidities, elevated hs‐CRP or increased ALT are significantly more likely to develop severe pneumonia as disease progresses." (PMID 32893398, 2020). "Neutrophil proportion, NLR, IL-6, ESR, CRP, and procalcitonin were generally higher in the pneumonia patients than in the pneumonia-free patients, in contrast to CD8+ and CD4+ T lymphocyte counts." (PMID 33239109, 2020). "This study is aimed at assessing the diagnostic value of hs-CRP, PCT, and IL-6 in differentiating severe pneumonia caused by RSV alone and RSV with bacterial coinfections among Vietnamese children under 5 years old." (PMID 32462018, 2020). "When CXR was performed for patients with pneumonia or acute bronchitis, CRP was analysed in 81.1% of the cases." (PMID 32127365, 2020). "The ratio CRP/NP has been proposed to discriminate an exacerbation of chronic obstructive pulmonary disease (COPD) from pneumonia." (PMID 32997689, 2020). "Considerably raised CRP values have typically occurred in patients with pneumonia, and high CRP levels were revealed to be a good predictor of disease in general practice." (PMID 33281906, 2020). "The mean CRP value among children with pneumonia and severe pneumonia was 14.13 (±0.59); 95% CI 12.95–15.32 and 21.38 (±0.56); 95% CI 20.26–22.51, respectively (p < 0.001)." (PMID 32605136, 2020). "Data regarding use of C-reactive protein (CRP), chest x-rays (CXRs), microbiological tests, and antibiotic prescriptions were assessed for patients aged 18–79 years, with the diagnosis pneumonia, acute bronchitis, or cough." (PMID 32127365, 2020). "Recent studies have shown that CRP levels can be used in the early diagnosis of pneumonia, and patients presenting with severe pneumonia had high CRP levels upon SARS-CoV-2 infection." (PMID 33244370, 2020). "We have analyzed the type of pneumonia, white cell count, C reactive protein levels and radiological findings in the two groups of patients- who recovered with first line of antibiotics and those who needed beyond." (PMID 32855902, 2020). "Our results indicate that CRP testing highly influences the physician’s degree of suspicion of pneumonia in primary care and that it seems to be of most value when not sure of the diagnosis." (PMID 33399009, 2020). "When interpreting the results, symptom duration should be considered as a factor, i.e. patients with symptoms of pneumonia should be treated if CRP is >100 mg/L at the visit or if CRP is <20 mg/L, and symptoms for more than one week." (PMID 33399009, 2020). "Use of CRP and microbiological tests in the diagnostics of LRTIs increased despite the fact that the incidence of pneumonia and acute bronchitis was stable." (PMID 32127365, 2020). "The CRP serum level is routinely measured in early diagnosis of pneumonia, and some Chinese publications have reported the prognosis value of CRP." (PMID 33312067, 2020). "This register-based study on LRTIs shows that the use of CRP testing increased from 53.4% to 65.7% in the assessment of patients with acute bronchitis and from 61.3% to 77.5% for patients with pneumonia from January 2006 to December 2014." (PMID 32127365, 2020). "AUROC for pneumonia diagnosis was 0.64 (95% CI: 0.56–0.72) for CRP; 0.59 (95% CI: 0.51–0.68) for PCT; 0.60 (95% CI: 0.52–0.69) for SAA; 0.41 (95% CI: 0.32–0.49) for NP; 0.63 (95% CI: 0.55–0.71) for CRP/NP and 0.61 (95% CI: 0.53–0.70) for SAA/NP." (PMID 32997689, 2020).
pneumonia (continued). "The main finding in this study is that the physician’s degree of suspicion appears to be highly influenced by CRP result when pneumonia is suspected in patients consulting primary care for LRTI symptoms." (PMID 33399009, 2020). "In analyzing factors associated with liver enzyme elevation, we found that not only the factors about the severity of pneumonia (CRP, oxygenation, and intubation) but also GS was a significant factor associated with the elevation of liver enzyme." (PMID 33147270, 2020). "For instance, there is evidence that the CRP-level at index consultation predicts severity and outcome of pneumonia in the elderly population." (PMID 32103747, 2020). "Most patients diagnosed with pneumonia had a CRP above 26 mg/L, while most patients diagnosed with acute bronchitis had a CRP below 25 mg/L." (PMID 31650886, 2020). "The MPV correlated with C-reactive protein (CRP) levels in patients with pneumonia as well as tuberculosis." (PMID 32802052, 2020). "After CRP result, the physician was ‘sure’ of the diagnosis of pneumonia in 55 patients (median CRP 112 mg/L), ‘quite sure’ in 68 cases (median CRP, 63 mg/L) and unsure in 64 cases (median CRP, 23 mg/L)." (PMID 33399009, 2020). "It has been shown that GPs who use CRP testing in the diagnosis of pneumonia often overestimate the probability of radiographic pneumonia." (PMID 33399009, 2020). "Studies in the general practice population showed CRP to be the strongest predictor of pneumonia, and that the reliability of the diagnosis improves when CRP is added to the evaluation of clinical signs and symptoms." (PMID 32103747, 2020). "The baseline clinical characteristics were not significantly different except the degree of inflammation (lower albumin and higher CRP) in patients with GS, pneumonia, and intubation." (PMID 33147270, 2020). "C-reactive protein (CRP) levels have been reported to alter with the development of symptoms, such that patients with severe pneumonia present high CRP levels." (PMID 32582747, 2020). "Early COVID‐19 patients with chronic comorbidities, elevated hs‐CRP or elevated ALT are significantly more likely to develop severe pneumonia as the disease progresses." (PMID 32893398, 2020). "Serum CRP levels are clinically used to differentiate pneumonia from other acute respiratory infections." (PMID 33149723, 2020). "According to univariate analyses, independent predictors for pneumonia included age, cough, sore throat, productive cough, and CRP level." (PMID 33187475, 2020). "Use of CRP increased during the study period from 61.3% to 77.5% for patients with pneumonia (P<0.001), and from 53.4% to 65.7% for patients with acute bronchitis (P<0.001)." (PMID 32127365, 2020). "Contrary, most patients had a C-reactive protein (CRP) test performed (pneumonia: 83%; acute bronchitis: 71%)." (PMID 31650886, 2020). "CRP was used more often when a patient was diagnosed with pneumonia (71.4%) compared to when a patient was diagnosed with acute bronchitis (61.9%; P<0.001)." (PMID 32127365, 2020). "A study conducted in Mozambique including children <5 years with severe pneumonia compared the use of procalcitonin and CRP as markers of bacteremia, confirmed with the performance of blood cultures." (PMID 32435627, 2020). "In the present study, median CRP serum levels were found to be significantly increased in pneumonia patients from the BL investigation timepoint, reaching a plateau at 48 h and decreasing again till the 120-h investigation." (PMID 33240188, 2020). "The present study aimed to evaluate the impact of CRP-result on the physician’s degree of suspicion of pneumonia in primary care." (PMID 33399009, 2020). "Pneumonia (13.8%) and urosepsis (6.2%) initially presented with either S2 with normal CRP or S3 but had poor prognosis." (PMID 32134948, 2020).
pneumonia (continued). "For patients with pneumonia, the median CRP value was 62 mg/L (interquartiles, 27 and 107 mg/L), and did not change over time (P = 0.22); the median CRP value for patients with acute bronchitis was 11 mg/L (interquartiles, 8 and 29 mg/L)." (PMID 32127365, 2020). "The CRP rise on day three correlated positively with the occurrence of postoperative pneumonia (r = 0.335, p = 0.005)." (PMID 32660083, 2020). "In patients with severe pneumonia, apolipoprotein-A1 decrease was associated with acute inflammation and the “cytokine storm” with an increase in IL6 and acute phase proteins such as CRP and haptoglobin." (PMID 33216772, 2020). "As many as 83.1% of patients diagnosed with pneumonia and 71.4% of the patients diagnosed with acute bronchitis had a CRP test performed." (PMID 31650886, 2020). "When chest sounds are abnormal at auscultation, the physician seems to tend to suspect pneumonia both before and after CRP testing." (PMID 33399009, 2020). "The chest X-ray is the gold standard for the detection or exclusion of pneumonia, while clinical features, including a low CRP value, can safely exclude pneumonia." (PMID 31455104, 2019). "This mainly concerns patients with clinical characteristics fitting with pneumonia that have an elevated CRP value." (PMID 31455104, 2019). "NGAL/Lpc-2, CRP, and von Willebrand factor (vWF) levels were shown to be significantly increased in children with severe pneumonia." (PMID 31183362, 2019). "For example, the positive predictive value of the CRP test to diagnose radiological pneumonia in children with fever and cough drops from 54% to 32% when fast breathing is removed from the algorithm." (PMID 31388660, 2019). "Although the use of PCT and CRP as biomarkers for discriminating bacterial infection has been discussed in various studies, these biomarkers cannot be used for true diagnosis of pneumonia." (PMID 31183362, 2019). "Secondly, radiologically confirmed pneumonia was associated with the indicators of a severe bacterial infection, WBC over 15 × 109/L and CRP over 100 mg/l." (PMID 30991957, 2019). "The clinical cases described in our study have in common a particularly severe presentation with a very high CRP and sometimes signs of septic shock with pneumonia or pericarditis." (PMID 31277095, 2019). "In contrast, serum CRP and procalcitonin level was significantly lower in patients with AE-IIPs than in those with pneumonia superimposed on CF-IIPs." (PMID 31852459, 2019). "This study also shows that GPs using the CRP POCT frequently use it for infections other than pneumonia." (PMID 31455104, 2019). "Use of pulse oximetry screening for detection of severe pneumonia, and host biomarker point of care tests (POCTs) like C-reactive protein (CRP) and procalcitonin (PCT) for detection of bacterial pneumonia, are being investigated." (PMID 31388660, 2019). "The score predicting confirmed pneumonia assigned one point for the presence of acute cough, male gender, a C-reactive protein >70 mg /L, and urea <7 mmol/L." (PMID 30991716, 2019). "While 73% of cases with definite bacterial pneumonia had both fever and elevated CRP (≥72 mg/L), only 11% of presumed viral plus other pneumonias and 10% of presumed viral pneumonias did." (PMID 30940126, 2019). "Children of our febrile control group showed more severe infections as indicated by significantly higher CRP values and higher percentage of pneumonia compared to upper respiratory tract infections in the FS group." (PMID 30605489, 2019). "A multicountry European study showed enhanced pneumonia prediction in patients in primary care presenting with acute cough when CRP testing was added to a clinical algorithm based on symptoms alone." (PMID 30554748, 2019). "The pneumonitis was distinguished from pneumonia by sputum culture plus laboratory C-reactive protein (CRP) and procalcitonin level." (PMID 30911841, 2019).
pneumonia (continued). "In general the different kinetics such as a short half-life, especially for MR-proADM, make markers like PCT and MR-proADM of less value than CRP when it comes to diagnose and treat pneumonia in general practice." (PMID 31747890, 2019). "The most widely studied area is measurement of the PCT and CRP levels in patients with pneumonia among those infected with the 2009 H1N1 influenza virus." (PMID 31183362, 2019). "Overall, based on diagnostic odds ratio, cough, crackles, respiratory rate ≥20 min−1, fever with temperature ≥ 38 °C, pulse rate >100 min−1, decreased breath sounds, CRP and PCT were potential useful diagnostic indicators of pneumonia." (PMID 31110214, 2019). "Pneumonia was associated with a WBC over 15 × 109/L (P = .006) and a CRP value over 80 mg/l (P < .05)." (PMID 30991957, 2019). "Patients present with pneumonia and pleural effusion signs in the chest x-ray and the combination of serum calprotectin and CRP constitutes a more highly sensitive and specific assay for identifying CPPE and empyema." (PMID 31215423, 2019). "In our results, biomarker such as PCT and CRP were the strongest predictors among all variables tested and had significant discriminating power than clinical signs and symptoms for pneumonia." (PMID 31110214, 2019). "The score incorporated four variables independently predicting confirmed pneumonia: male gender, acute cough, C-reactive protein >70 mg/L, and urea <7 mmol/L." (PMID 30991716, 2019). "The median blood CRP concentration was more than 6 times higher in definite bacterial cases than in presumed viral (174 versus 24 mg/L; p < 0.001) and other pneumonia cases (174 versus 27 mg/L; p < 0.001)." (PMID 30940126, 2019). "CRP predicts pneumonia better than the other biomarkers but adding CRP to the clinical model did not improve classification (− 4%); however, CRP helped guidance of the decision which patients should be given antibiotics." (PMID 31747890, 2019). "CRP was found to have capacity to distinguish definite bacterial pneumonia from presumed viral and other pneumonia." (PMID 30940126, 2019). "For this reason, and to increase the number of children available for comparator standards, we defined four children with pneumonia, high CRP and NP carriage of serotype 1 as pneumococcal pneumonia." (PMID 32039044, 2019). "In adult populations, only relatively high CRP values have been shown useful in predicting the presence of pneumonia, and a cut-off value of 100 mg/l is mentioned in some studies." (PMID 30991957, 2019). "Our study strengthens the idea that high CRP and WBC values are associated with pneumonia in patients with respiratory symptoms but have limited value as independent predictors." (PMID 30991957, 2019). "A recent meta-analysis ascertained that even when clinical variables are taken into account, the CRP test can help to confirm or exclude pneumonia." (PMID 31455104, 2019). "Median CRP levels of moderate and severe pneumonia increased by 1.6 and 74.9%, respectively, compared with those of mild pneumonia in younger patients." (PMID 30616612, 2019). "For comparison, the common biomarkers used in infection were included for analysis and correlation between CRP and pneumonia severity were also analyzed." (PMID 31091284, 2019). "Next, we investigated the relationship between pneumonia severity and PCT levels, CRP levels, and WBC counts in elderly patients in which pneumonia was caused by S. pneumoniae, the most common pathogen identified in the study." (PMID 30616612, 2019). "As for those patients undergoing cardiac surgery, endocan instead of procalcitonin or CRP has been suggested as a useful early marker for postoperative pneumonia." (PMID 31065299, 2019). "The participating doctors would thus describe common risks of co-infection and that: “If [the CRP test result is] low and [the patient’s] condition is bad, and there is bacterial infection, what we fear most in the bacterial infection is the pneumonia." (PMID 30736818, 2019).
pneumonia (continued). "CRP is a well-established biomarker in many clinical settings, but has been traditionally considered insufficient as a useful marker in the diagnosis of pneumonia." (PMID 30285748, 2018). "POC CRP testing has added value in the diagnosis of pneumonia in adults, and has proven to safely reduce antibiotic prescriptions in general practice." (PMID 30564733, 2018). "The diagnosis of pneumonia was corroborated by the lower oxygen saturation (p 0.001) and higher CRP values (p 0.023) of these patients compared to those with uncomplicated bronchiolitis, together with their prompt response to antibiotic therapy." (PMID 30526548, 2018). "So far, most studies focused on the diagnostic performance of serum biomarkers, especially CRP and PCT on the pneumonia diagnosis." (PMID 30285748, 2018). "We assessed the serum CRP level with the exclusion of six patients in whom an inflammatory complication occurred (anastomosis leakage, surgical site infection, and pneumonia)." (PMID 29892933, 2018). "This was especially true when CRP was over 100 mg/L, or if there was a new infiltrate on the chest X-ray indicating pneumonia." (PMID 28516200, 2017). "Among HIV-positive CXR+ cases, CRP ≥40 mg/L was similarly more common among older children and those with very severe pneumonia (P = .01 and P = .03, respectively, adjusted for site and age; data not shown)." (PMID 28575375, 2017). "White blood cell counts and C-reactive protein levels were also significantly higher in pneumonia patients." (PMID 28545080, 2017). "High serum CRP and low serum albumin at the onset of bacteremia are predictive of disease progression to pneumonia and poor prognosis." (PMID 28938875, 2017). "A CRP value above 50 mg/L (mean CRP of 97 mg/L, 95% CI 49–145) in hospitalised patients with AECOPD is associated with pneumonia and such patients are likely to benefit from antibiotics." (PMID 28969667, 2017). "Results from these previous studies have suggested higher cut‐off values of CRP in pneumonia than the one in this study, the value perhaps being lower due to the incomplete availability of X‐rays." (PMID 27935664, 2017). "This is a remarkable finding since most reported biomarkers (e.g., procalcitonin, C-reactive protein) increase during pneumonia." (PMID 28218729, 2017). "We measured serum CRP levels in cases with World Health Organization–defined severe or very severe pneumonia and a subset of community controls." (PMID 28575375, 2017). "Lack of a gold standard for identifying bacterial and viral etiologies of pneumonia has limited evaluation of C-reactive protein (CRP) for identifying bacterial pneumonia." (PMID 28575375, 2017). "Among allo-HSCT recipients with S. maltophilia bacteremia, low albumin and high CRP levels appear to be predictive of disease progression to pneumonia and poor prognosis." (PMID 28938875, 2017). "We evaluated the sensitivity and specificity of CRP for identifying bacterial vs respiratory syncytial virus (RSV) pneumonia in the Pneumonia Etiology Research for Child Health (PERCH) multicenter case-control study." (PMID 28575375, 2017). "Among 9 patients with both high CRP and low albumin, 5 had pneumonia at the onset of bacteremia and the remaining 4 patients developed pneumonia in a median of 3 days (range, 1 to 8 days) even under effective treatment." (PMID 28938875, 2017). "CRP was significantly higher in children with IMCI pneumonia/positive urine or blood culture (mean 41.0 mg/l, 95% CI 28.3–53.6 median 16 mg/l) vs. children without any signs of bacterial infection (mean 23.8 mg/l, 95% CI 17.8–27.8, median 7 mg/l)." (PMID 27935664, 2017). "Subjects with a final diagnosis of pneumonia had higher serum CRP levels (median 187 mg/L) than those with exacerbations of chronic obstructive pulmonary disease (63 mg/L) or acute bronchitis (54 mg/L, p < 0.01)." (PMID 27610265, 2016).